ENSG00000274520
Gene: Miscellaneous RNA gene on chromosome 2 (44,932,320 to 44,932,406, forward strand). Ensembl gene ENSG00000274520.
Gene Ontology:
Biological process: regulation of gene expression
Homologues: Orthologues: mouse Gm55781 (78% identical).